REC8 (REC8 meiotic recombination protein)
Diseases named in the same sentence as REC8 in open-access papers (continued):
Sharing a sentence is not in itself a finding about the gene and the disease.
tumor (21 papers, 2013 to 2023). "Another study showed that epigenetic alterations in EBV-positive GC downregulated meiotic recombination protein Rec8 in 100% of the cases examined, thereby causing loss of its tumor-suppressive effect." (PMID 29691341, 2018). "On the analysis of the TCGA database, we observed an association between REC8 hypermethylation and high tumor stages (T)." (PMID 26472282, 2015). "Moreover, REC8 expression was associated with poor tumor prognosis in patients, which is not only attributed to cell growth and migration caused by REC8 reduction, but also promoted EGR1-mediated EMT." (PMID 32958054, 2020). "The low expression of ZNF880 leads to a decrease in the expression of REC8 and thus limits the tumor suppressor activity of REC8." (PMID 37370088, 2023). "In our study, REC8 showed significant hypermethylation in tumor tissue for the BRAF wild-type group when compared to the BRAF mutant group." (PMID 36975440, 2023). "REC8 has been shown to have tumor suppressor activity in a variety of cancers and is a new type of tumor suppressor gene." (PMID 37370088, 2023). "REC8-augmented expression induced mitotic catastrophe and the generation of endopolyploid tumor cells." (PMID 35251135, 2022). "REC8 meiotic recombination protein (REC8) inhibits tumor angiogenesis by inhibiting NF-κB mediated expression of vascular endothelial growth factor." (PMID 34753383, 2021). "It is noteworthy that VEGF secreted by cancer cells acted as chemoattractants in promoting motility of endothelial cell during tumor angiogenesis, which focused us to seek the potential role of REC8 on VEGF expression." (PMID 32958054, 2020). "Further studies are required to elucidate the role of REC8 in tumor immunology, tumor differentiation, tumor metabolism and remodeling tumor microenvironment." (PMID 32958054, 2020). "REC8 has a more consistent tumor suppressive role and promoter hypermethylation and suppression of its expression occurs in tumor cells." (PMID 31149338, 2019). "A similar trend of REC8 methylation level in the tumor ranking order was observed when different cut-off values for the methylation were used, particularly at high cut-off values of X ̄+3SD and X ̄+4SD." (PMID 26472282, 2015). "REC8 methylation level in each of the four tumor types was higher than the methylation level of 279.41 ± 171.28 in the normal tissue (p < 0.001)." (PMID 26472282, 2015). "Their findings suggest that REC8 may have tumor suppressor effects and act as a robust epigenetic target of the PI3K pathway." (PMID 36975440, 2023). "In summary, these results showed that the critical role of REC8 in mediating tumor angiogenesis." (PMID 32958054, 2020). "Moreover, in polyploid tumour cells, we found structures resembling karyospheres (karyosomes) of maturing oocytes acting in cooperation with REC8 and MOS in the formation of the centromere cluster around and then beside the nucleolus." (PMID 30691027, 2019). "The anti-tumour effects of Rec8 are caused by downregulation of cell growth-related genes (G6PD, SLC2A1, NOL3, MCM2, SNAI1, and SNAI2) and also by upregulation of both apoptosis or migration inhibitors (Gadd45G and LDHA) and tumour inhibitors (PinX1, IGFBP3, and ETS2)." (PMID 36139540, 2022). "However, the role of REC8 as a tumor suppressor remains elusive and further studies are needed to decipher how reactivation of a cohesin protein could protect cells from cancer progression." (PMID 35251135, 2022). "In these cases, Maguire suggested the presence of rudimentary small SCs located between cohesed centromeres and pointed out that REC8 conserved through evolution since the proto-eukaryotes may be involved, which we consistently found in tumours at these same sites." (PMID 30691027, 2019).
tumor (continued). "In particular, polyploid tumor cells can undergo depolyploidization that is accompanied by upregulation of SPO11 and REC8 genes." (PMID 31558727, 2019). "When analyzed in individual tumor types, PI3K+ ATC had significantly higher REC8 methylation than that in the PI3K- ATC (1294.21 ± 1059.85 vs. 721.22 ± 306.46, p = 0.023)." (PMID 26472282, 2015). "A body of emerging evidence has revealed that meiotic chromosome regulator genes, including REC8, SMC1β, RAD21L1, TEX19, HORMAD1, and SYCP3, are inappropriately activated to modulate chromosome maintenance and segregation in tumor development, maintenance, and spread." (PMID 34150762, 2021). "REC-8 localizes to the nucleus of germ cells in the mitotic cycle and REC-8 was nuclear throughout the tumor; PH3 marks M-phase and was seen in dividing cells throughout the tumor; and PGL-1 marks germ cells and also was found throughout the tumor." (PMID 29232700, 2017). "The current study provided a novel insight into the functional role of REC8 in tumor angiogenesis, suggesting REC8 serves as a negative regulator in tumor angiogenesis through suppressing NF-κB-mediated VEGF, and demonstrating a novel function of REC8 in tumor progression." (PMID 32958054, 2020). "Up to now, no available reports about the function of REC8 in tumor angiogenesis." (PMID 32958054, 2020). "Additionally, inhibition of NF-κB by NF-κB inhibitor BAY11-7082 treatment could reverse the promotion of REC8 knockdown in VEGF expression, leading to attenuate the tube formation, implying involvement of NF-κB in REC8 tumor biological function." (PMID 32958054, 2020). "However, there is no available reports about the function of REC8 on tumor angiogenesis." (PMID 32958054, 2020).
cancer (12 papers, 2006 to 2023). A tumor composed of atypical neoplastic, often pleomorphic cells that invade other tissues. "In polyploidy cancer cells, resulting from irradiation-induced mitotic catastrophe, REC8 was associated with centrosomes and spindle poles, further advocating for a role in depolyploidization." (PMID 27275820, 2016). "Although this analysis was carried out in only the 6 cancer cases, the correlations between deltaβ and time to diagnosis were significant for the CpGs in the promoter region of REC8, and introns of RPTOR and ZSWIM5." (PMID 31149338, 2019). "In a study of radiation-induced mitotic catastrophe in various cancer cell lines, genes specifically associated with meiosis were shown to be upregulated (i.e., SCP3, REC8 and DMC1)." (PMID 27275820, 2016). "Analysis of the TCGA data also revealed hypermethylation of the REC8 gene in many other human cancers." (PMID 26472282, 2015). "Our analysis of the TCGA data also showed hypermethylation and silencing of REC8 in many other human cancers." (PMID 26472282, 2015). "This is likely a mechanism involved in the PI3K pathway-promoted REC8 methylation in human cancers." (PMID 26472282, 2015). "With our strategy using strict criteria to explore genes with the most robust changes in methylation and expression and with the highest functional potential as a cancer gene on the Gene Ontology analysis, we identified REC8 as a particularly promising novel cancer-related gene." (PMID 26472282, 2015). "In this regard, REC8, SMC1β, and STAG3 have been found to be widely expressed in human cancers, whereas the expression of the RAD21L subunit is practically undetectable." (PMID 37443752, 2023). "Other genes, including DMC1, STAG3 and REC8, allow somatic cancer cells to escape radiation-induced cell death without directly affecting the intracellular DNA repair pathways." (PMID 35251135, 2022). "Similar relationship between REC8 and the PI3K pathway was also seen in some other cancers." (PMID 26472282, 2015). "A similar relationship between REC8 and the PI3K pathway was seen in several other cancers." (PMID 26472282, 2015).
benign tumors (1 paper, 2015). "For example, 23.33% FTC and 26.21% ATC had REC8 methylation higher than X ̄+4SD, whereas < 10% PTC and benign tumors reached this methylation level." (PMID 26472282, 2015).
REC8 also shares sentences with these, for which no sentence is quoted: breast carcinoma (3 papers); aneuploidy (1); Azoospermia (1); colon cancer (1); colorectal cancer (1); cyst (1); follicular thyroid cancer (1); gastrointestinal stromal tumor (1); hypopharyngeal carcinoma (1); leukoplakia (1); male infertility (1); schizophrenia (1); thyroid (1); viral infection (1).